MGMT (O-6-methylguanine-DNA methyltransferase)
Diseases named in the same sentence as MGMT in open-access papers (continued):
Sharing a sentence is not in itself a finding about the gene and the disease.
melanoma (continued). "Further, we determined the synergy between PA and DTIC in the MGMT-depleted melanoma cells and found that knockdown of MGMT compromised the synergistic effects, suggesting that MGMT was required for the synergistic cytotoxicity of PA and DTIC." (PMID 37024907, 2023). "Since MGMT activity is considered to be one of the key factors affecting cell resistance to alkylating agents, its expression was determined in melanoma cells in the present study." (PMID 36533319, 2023). "The results showed that MG132 not only slowed down intrinsic MGMT degradation in single cycloheximide treated cells but also attenuated PA-mediated MGMT degradation in the melanoma cells." (PMID 37024907, 2023). "The alkylating agent temozolomide has been shown to induce senescence in melanoma cells expressing MGMT." (PMID 36533319, 2023). "The results showed that the two melanoma cell lines elevated their MGMT levels in response to DTIC treatment." (PMID 37024907, 2023). "Our study demonstrates that the bioactive compound, Protocatechuic aldehyde, synergistically promotes the cytotoxicity of DTIC to melanoma cells through destabilization of MGMT protein." (PMID 37024907, 2023). "And PA reduced MGMT protein level by promoting its degradation in the two melanoma cell lines either by single usage or combination with DTIC." (PMID 37024907, 2023). "miR-650 also contributes to drug resistance, such as by upregulating dacarbazine (DTIC) resistance in melanoma through the lncRNA POU3F3/miR-650/MGMT (methylguanine-DNA-methyltransferase) axis, which turns miR-650 into a potential target for cancer treatment." (PMID 35331235, 2022). "In terms of the mechanism, lncRNA POU3F3 works as a competitive RNA to combine with miR-650; therefore, MGMT expression rises to a higher extent in melanoma cells." (PMID 35331235, 2022). "Endogenous competition between lncRNA POU3F3 and miR-650 regulates the expression levels of MGMT, which determines the tolerance of melanoma cells to DTIC treatment to some extent." (PMID 33816296, 2021). "A large number of genes have been identified as hypermethylated in melanoma, including O6-methylguanine-DNA methyltransferase (MGMT), cyclin-dependent kinase inhibitor 2A (CDKN2A), and Ras-association domain family 1 isoform A (RASSF1A)." (PMID 34944843, 2021). "In this study, a positive correlation was observed between lncRNA POU3F3 and the MGMT expression in DTIC-resistant melanoma cells in vivo and in vitro." (PMID 33816296, 2021). "Melanoma cells treated with temozolomide (TMZ) over two months upregulated the expression of MGMT and became TMZ resistant." (PMID 34299198, 2021). "Clinical trials identified elevated MGMT expression in melanoma metastases as an indicator for DTIC-based therapy resistance." (PMID 33816296, 2021). "This lncRNA directly sponges miR-650 to positively regulate the level of O6-methylguanine-DNA-methyltransferase (MGMT) oncogene in melanoma cells." (PMID 34638331, 2021). "We further accessed the correlation of lncRNA POU3F3 and MGMT in the DTIC resistance of melanoma cells." (PMID 33816296, 2021). "Our study suggested that the lncRNA POU3F3/miR-650/MGMT pathway is a novel target for improving the therapeutic efficiency of alkylating agents-based chemotherapy for melanoma." (PMID 33816296, 2021). "Molecular analysis indicated that lncRNA POU3F3 worked as a competitive endogenous RNA to regulate the levels of miR-650, and the lncRNA POU3F3/miR-650 axis determined the transcription of MGMT in melanoma cells to a greater extent." (PMID 33816296, 2021). "In temozolomide-resistant melanoma cells, MDA-7/IL-24 caused inhibition of O6-methylguanine-DNA methyltransferase (MGMT) resulting in enhanced temozolomide-induced cell killing." (PMID 35008495, 2021). "The MGMT methylation status can thus determine the outcome in melanoma patients treated with methylating drugs." (PMID 34944843, 2021).
melanoma (continued). "The hypermethylated state of MGMT has been detected in the cell lines, tissues, and serum of melanoma patients using MSP, real-time quantitative MSP, high-resolution melting point analyses (HRMA), pyrosequencing, and MS-MLPA." (PMID 34944843, 2021). "By detecting the methylation status of five genes (RASSF1A, p16, DAPK, MGMT, and Rb) in 34 tumors (including 15 melanoma primaries, 19 metastases), heterogeneous methylation was found in 70% of the cases." (PMID 34539742, 2021). "Hypermethylation in RARRES2 was 70% in both primary and metastatic melanoma, but RASSF1A, DAPK and MGMT had significantly lower hypermethylation in primary melanoma versus metastatic melanoma." (PMID 34441278, 2021). "The results showed that the ectopic miR-650 expression increased cell apoptosis, which also attenuated the MGMT-induced DTIC resistance in melanoma cells." (PMID 33816296, 2021). "This potent agent has been shown to reverse therapeutic resistance to TMZ by modulating MGMT expression in a variety of human tumor cell lines and xenograft models that include brain, melanoma, prostate and colon cancers." (PMID 33335215, 2020). "The sensitivity of melanoma cells to TMZ was negatively correlated with the expression levels of O6-methylguanine-DNA methyltransferase (MGMT), the enzyme to repair TMZ-induced DNA lesions." (PMID 32899791, 2020). "The sensitivity of melanoma cells to TMZ has been negatively correlated with their MGMT expression levels." (PMID 32899791, 2020). "In a previous paper, we analyzed the coexistence of MPM and oculocutaneous albinism and concluded that MGMT is a new player involved in melanoma pathogenesis." (PMID 33748184, 2020). "Melanoma cells are intrinsically resistant to TMZ due to the expression of O6-methylguanine-DNA methyltransferase (MGMT), the enzyme responsible for repairing DNA lesions induced by TMZ." (PMID 32899791, 2020). "We found that MGMT-negative melanoma cell cultures, before any drug treatment, already harbored a small fraction of MGMT-positive cells, which survived TMZ treatment and promptly became the dominant cell type within the surviving population." (PMID 30274152, 2018). "TMZ treatment of mice implanted with MGMT-negative melanoma cells resulted in effective tumor growth delay, but eventually tumor growth resumed, with tumor tissue having become MGMT positive." (PMID 30274152, 2018). "The key findings of our study are as follows: (i) two established melanoma cell lines, which appear to lack MGMT expression, in fact harbor a small percentage of MGMT-positive cells." (PMID 30274152, 2018). "A depletion in MGMT can be gained in melanoma cells when TMZ is administered at a low dose of 100–200 mg/m2 consecutively for 2 days." (PMID 29747595, 2018). "In melanoma, epigenetic silencing of this gene has been demonstrated in tumors and serum of patients, suggesting an important role of MGMT in tumor development." (PMID 29100458, 2017). "Melanoma hypermethylation prevalence for ERα (50%), MGMT (50%), RARB2 (44%), RIL (88%), RASSF1A (69%), PAX7 (31%), PGRB (56%), PAX2 (38%), NKX2-3 (63%), OLIG2 (63%), HAND1 (63%), ECAD (88%), CDH13 (44%), MLH1 (0%), and p16 (6%) was reported." (PMID 28396701, 2017). "MGMT mediates chemoresistance and is frequently seen in various solid tumors, including non-small cell lung carcinoma, melanoma and breast carcinoma." (PMID 28752860, 2017). "Detection of aberrantly methylated SOCS1/2, RASSF1A, MGMT, and CDKN2A in serum has been reported to have diagnostic value in patients with malignant melanoma." (PMID 28396701, 2017). "Methylation of the DNA repair protein MGMT was reported to predict response to temozolomide treatment in stage IV melanoma patients." (PMID 28396701, 2017).
melanoma (continued). "In distant melanoma metastasis, it has been reported that one-third of the patients had MGMT hypermethylation." (PMID 27247816, 2016). "Another recent study demonstrated the O6-methylguanine-DNA-methyltransferase (MGMT) promoter methylation status determined by PCR in tumor tissue from primary melanomas as a predictive marker of response to temozolomide, an oral derivative of DTIC." (PMID 26799424, 2016). "Additional studies in melanomas are necessary to clarify the role of the observed methylation changes in the expression of the MGMT gene." (PMID 26106605, 2015). "Germline mutations in additional genes were recently associated with melanoma occurrence: MITF, BAP1, TERT promoter, POT1, and MGMT." (PMID 26106605, 2015). "In this experimental setting the response of melanoma cells depleted in MGMT was assessed in order to elucidate the influence of vemurafenib on the O6-alkylguanine response." (PMID 25557167, 2014). "Since melanomas express low amounts of MGMT they are expected to respond to alkylating agent based therapy, which is likely the reason why DTIC, TMZ and FM have been approved for therapy." (PMID 25557167, 2014). "d) Does vemurafenib treatment change the MGMT promoter methylation status of melanoma tumors in vivo?" (PMID 25557167, 2014). "Mice bearing A375P melanoma tumor cells were treated by IL injection with either 25 ug of MGMT-kB1 LODN or control ODN or vehicle (5% glucose)." (PMID 25460932, 2014). "Despite low MGMT levels in melanoma, the response rate with these genotoxic anticancer drugs remains low and the therapeutic outcome poor." (PMID 25557167, 2014). "The expression of MGMT in melanomas is controlled by the methylation status of CpG islands in its promoter." (PMID 25557167, 2014). "This work demonstrates for the first time that, in melanoma, silencing of the MGMT promoter correlates with TMZ toxicity." (PMID 20736948, 2010). "In advanced melanoma MGMT promoter, methylation correlates with tolerance of therapy, but not with clinical outcome." (PMID 20736948, 2010). "Our results, and those of others using O6-benzylguanine, hold out little hope for MGMT inactivation in the effective treatment of melanoma." (PMID 19367282, 2009). "In the phase 1 study of LM/TMZ, we observed complete inactivation of tumour MGMT after a single dose of LM in three of five patients with melanoma and >96% inactivation in the other two." (PMID 19367283, 2009). "The data are in line with other reports showing that MGMT protects in vitro against TMZ-induced melanoma cell death." (PMID 19127257, 2009). "We evaluated the pharmacodynamic effects of the O6-methylguanine-DNA methyltransferase (MGMT) inactivator lomeguatrib (LM) on patients with melanoma in two clinical trials." (PMID 19367283, 2009). "Despite the wealth of pre-clinical data to support MGMT's role in determining the outcome of methylating agent treatment in melanoma, evidence for the protein's importance in the clinic is inconclusive." (PMID 19367282, 2009). "MGMT inactivation by O6-benzylguanine sensitized all melanoma cell lines expressing MGMT to TMZ and fotemustine-induced apoptosis, and MGMT transfection attenuated the apoptotic response." (PMID 19127257, 2009). "Methylation status of the MGMT promoter as assessed by MS-PCR as well as the MGMT immunoprofile was available from 178 tumor samples (27 metastases of renal cell carcinoma, 39 of breast carcinoma, 36 of lung carcinoma, and 76 of malignant melanoma)." (PMID 19274096, 2009). "It appears that melanoma cells are intrinsically resistant and acquire drug resistance by different strategies in which MGMT is only one of several players." (PMID 19127257, 2009). "We have found MGMT activity along with its substrate DNA lesion, O6-meG, in the same melanoma biopsy in a previous trial." (PMID 19367283, 2009). "Melanoma biopsies taken in the 24–72 h after patients finished their first cycle of lomeguatrib and temozolomide showed residual MGMT activity." (PMID 19367282, 2009).
melanoma (continued). "In this study, we demonstrate that about 30% of brain metastases originating from renal, breast and lung cancer as well as from malignant melanomas reveal a methylated MGMT-promoter." (PMID 19274096, 2009). "Under MGMT-depleted conditions, the cells approached the sensitivity of MeWo cells not expressing MGMT indicating that O6-chloroethylguanine, which is subject to repair by MGMT, is responsible for fotemustine-induced apoptosis in melanoma cells." (PMID 19127257, 2009). "Total depletion of MGMT occurred in three of five subcutaneous melanoma metastases analysed 4 h after the first dose of lomeguatrib, and >96% depletion was observed in the other two." (PMID 19367282, 2009). "In a melanoma study with the same regimen, tumour biopsy analysis suggested early recovery of MGMT activity, within 24 h, even when lomeguatrib doses were increased to 60 and 80 mg per day." (PMID 18475294, 2008). "We have previously shown that human melanoma xenografts expressing moderate levels of MGMT do respond to growth inhibition by temozolomide, but this is considerably enhanced by pretreatment with PaTrin-2." (PMID 16278661, 2005). "In a previous study, we evaluated MGMT expression in human melanoma metastases, and saw a tendency of lower MGMT expression in responders to DTIC-based chemotherapy compared with nonresponders." (PMID 14562026, 2003). "Analysis of MGMT expression in biopsies of melanoma metastases was performed by immunohistochemistry using the MT 3.1 monoclonal human anti-MGMT antibody." (PMID 14562026, 2003). "Single nucleotide polymorphisms in the coding regions of the MGMT gene have also been analysed to investigate the possible relevance of MGMT SNPs for response to chemotherapy in melanoma patients." (PMID 14562026, 2003). "The fact that only 50% of the responders with single-agent DTIC therapy had tumours with <50% MGMT-positive tumour cells, indicates that other additional factors are involved in response to chemotherapy in these melanoma patients." (PMID 14562026, 2003). "In a clinical trial of temozolomide in advanced malignant melanoma, the relationship between pretreatment MGMT levels in biopsies of cutaneous tumours and involved lymph nodes and clinical response to the drug has been studied." (PMID 9820180, 1998). "Tumour samples obtained from one primary melanoma and several lymph node and skin metastases were analysed for O6-methylguanine-DNA methyltransferase (MGMT) activity." (PMID 7819045, 1995). "Therefore, we confirmed that the mechanism of acquisition of TMZ in melanoma is mainly through affecting the transcription of MGMT." (PMID 39873425, 2025). "The promotion of MGMT transcription after TMZ action may be a mechanism of acquired drug resistance in melanoma cells." (PMID 39873425, 2025). "Compared to other types of cancer, melanoma expresses quite low levels of MGMT, similar to malignant glioma, which might explain why melanomas respond to the methylating drugs DTIC and TMZ." (PMID 39873425, 2025). "The MGMT(+) melanoma cell lines, WM852 and WM266-4, showed mostly methylated promoters." (PMID 38811596, 2024). "Likewise, the two MGMT(−) melanoma cell lines, A375 and MM415, showed mixed methylated/unmethylated results for their promoters." (PMID 38811596, 2024). "Thus, MGMT expression was associated with both senescence and quiescence induction in SK‐MEL‐2 melanoma cells." (PMID 36533319, 2023). "To address how PA regulated MGMT expression in melanoma cells, we first assayed MGMT mRNA expression in the two melanoma cell lines after receiving PA treatment for 72 h and found no significant changes at the mRNA level, suggesting that PA did not transcriptionally regulate MGMT." (PMID 37024907, 2023). "In addition, the lncRNA POU3F3/miR-650/MGMT pathway has been revealed to function critically in DTIC resistance in melanoma." (PMID 35331235, 2022).
melanoma (continued). "Furthermore, a decreased MGMT expression was observed with the miR-650 mimic transfection in DTIC-resistant melanoma cells, which was examined with qRT-PCR assays and Western blot assays." (PMID 33816296, 2021). "We evaluated the expression status of lncRNA POU3F3/miR-650/MGMT in melanoma tissues." (PMID 33816296, 2021). "As melanomas are likely to express low levels of MGMT, this could explain why they respond to methylating drugs, including DTIC and TMZ, but not to other anti-cancer drugs." (PMID 34944843, 2021). "Altogether, these data suggest that MGMT-low melanoma cells are sensitive to TMZ treatment." (PMID 32899791, 2020). "Similarly, MGMT expression levels were increased when MGMT-low melanoma cells became resistant to TMZ, suggesting that increased DNA repair supported the acquired resistance to the DNA alkylating agent in these cells." (PMID 32899791, 2020). "Although a significant correlation of MGMT expression and melanoma resistance to temozolomide has been recognized, clinical trials with added MGMT inhibitors (O6BG or lomeguatrib), were unable to demonstrate substantial improvement upon TMZ’s mediocre therapeutic activity." (PMID 30274152, 2018). "In addition, epigenetic inactivation of MGMT has been demonstrated in melanoma tumor tissue and in the serum of melanoma patients." (PMID 27776349, 2017). "In our study, we detected methylation differences at MGMT body both in peripheral blood and in tumor samples: CDKN2A-mutated patients showed a low-level hypermethylation in leukocytes compared to other melanoma patients, while tumors showed hypomethylation compared to melanocytes." (PMID 26106605, 2015). "Initial assessment in 10 melanoma cell lines revealed that TMZ resistance correlated with MGMT expression (r = 0.79, p = 0.009), and in MGMT-proficient cell lines, with phospho-IGF-1R (r = 0.81, p = 0.038), suggesting that TMZ resistance associates with IGF-1R activation." (PMID 26497996, 2015). "MGMT downregulation is associated, as here, with melanoma sensitivity to TMZ in vitro, although not clinically." (PMID 26497996, 2015). "Therefore, the influence of vemurafenib therapy on the silencing of MGMT in melanomas was investigated by determining the promoter methylation status in tumor specimens." (PMID 25557167, 2014). "The role of MGMT as a predictive marker of response to alkylator-based chemotherapy in melanoma is much less defined, and MGMT may in fact be more valuable for the prediction of toxicity." (PMID 21811257, 2011). "The contribution of MGMT to melanoma resistance to methylating agents seems to be rather dependent on downstream pathways that are capable of recognising the persistent O6-guanine base damage and initiating apoptosis, such as the DNA mismatch repair pathway (MMR)." (PMID 21811257, 2011). "For melanoma, few studies, with limited numbers of patients, have analysed MGMT activity and most of these did not focus on MGMT gene methylation, but on MGMT protein expression levels and MGMT activity." (PMID 20736948, 2010). "Because DTIC and TMZ are still the standard therapy for melanoma, however, determination of MGMT methylation could indicate for which patients these treatments should not be given, because of expected toxicity." (PMID 20736948, 2010). "Hence, the MGMT methylation status seems not to change with clinical course, and for evaluation of the MGMT methylation status of the patient's melanoma the primary or a metastasis can be taken." (PMID 20736948, 2010). "Toxicity is in contrast with response of melanoma correlated with MGMT activity." (PMID 20736948, 2010).